FAM41AY2 (family with sequence similarity 41 member A, Y-linked 2 )
Gene: Long non-coding RNA gene on chromosome Y (18,388,843 to 18,405,046, reverse strand). Ensembl gene ENSG00000290726.
Homologues: Paralogues in human: FAM41AY1 (100% identical).